MTOR (mechanistic target of rapamycin kinase)
Diseases named in the same sentence as MTOR in open-access papers (continued):
Sharing a sentence is not in itself a finding about the gene and the disease.
infection (504 papers, 2010 to 2026). The state of being infected such as from the introduction of a foreign agent such as serum, vaccine, antigenic substance or organism. "gondii infection caused broad suppression of Akt/mTOR signaling, with 6 of 8 markers significantly downregulated, including pS6RPSer235/236, pAKTS473, pBADSer136, pIRS1S636/639, pPTENSer380, and pGSK-3α/βSer21/9." (PMID 42193903, 2026). "Targeting mTOR in innate immune cells therefore represents an attractive approach to manage infection-associated hyperinflammation." (PMID 40177636, 2025). "Collectively, these findings demonstrate that bitter taste signaling deficiency leads to the activation of mTOR pathway, reduces eNOS expression, and retards the recovery process at D14 post-infection." (PMID 41142782, 2025). "An mTOR inhibitor was associated with a reduced infection risk (OR 0.27 [CI: 0.09–0.70], p = 0.009)." (PMID 40573897, 2025). "Several clinical trials have proved systematic use of mTOR inhibitors enhances immune function, reduces infections in the elderly, and decreases the risk of CMV and polyomavirus infection in solid organ transplant recipients." (PMID 39114448, 2024). "Phosphorylations of the PIKK kinases ATR (T1989) and MTOR (T1162) were upregulated by infection with all variants." (PMID 39653747, 2024). "Our study shows that this susceptibility to S.aureus infection during mTOR suppression is due to animpaired function of phagocytic immune cells responsible for controllingbacterial infections." (PMID 38767353, 2024). "Activation of mTOR is alsoinvolved in the immune response to bacterial infection, and treatmentsthat inhibit mTOR are associated with increased susceptibility tobacterial infections in the skin and soft tissue." (PMID 38767353, 2024). "Further studies are warranted to validate the role of mTOR antagonists, tailoring immunosuppression based on the risk of rejection, infection, and malignancies including PTLD." (PMID 35282339, 2022). "mTOR-deficient macrophages had lower baseline mROS and a muted infection-induced increase, which only reached baseline WT levels." (PMID 36103894, 2022). "Nevertheless, various inhibitors of mTOR have been shown to induce autophagy and cause cellular stress, with such factors as starvation and intracellular infection inhibiting mTORC1." (PMID 35531887, 2022). "As an immunosuppressant, blocking mTOR (notably with the use of sirolimus) is linked to development of cancer (especially lymphoma and skin cancer), infections and other adverse events including hyperglycemia and dyslipidemia." (PMID 35154105, 2022). "mTOR-deficient macrophages tolerate infection with mycobacteria so long as they lack functional ESAT-6." (PMID 36103894, 2022). "Worthy to note that the levels of AKT and mTOR are increased in QKI deficiency macrophage after infection, it indicated that the increased pathogen removal effects were independent on the classical mTOR pathway." (PMID 36088389, 2022). "Key genes including elongation initiation factor pathway genes, GSK3B, and regulatory associated protein of mTOR (RPTOR) genes that protect cells from infection were significantly downregulated in Native Hawaiians." (PMID 36450776, 2022). "Consistent with defective mitochondrial metabolism, mTOR-deficient macrophages had slightly lower baseline ATP production, again with a muted infection-induced increase that only reached baseline WT levels." (PMID 36103894, 2022). "We selected the AMPK and mTOR signaling pathways to find the metabolism and immunity-related changes caused by infection and the effect of cinnamaldehyde treatment on the expression level of the genes involved in these pathways." (PMID 35847587, 2022). "Inhibition of the mTOR pathway is associated with an increased incidence of infection, resulting in an increased number of subjects receiving antibiotics compared to the control subjects in ten Phase I Clinical Trials." (PMID 35897089, 2022).
infection (continued). "If so, then inhibition of glycolysis should phenocopy mTOR deficiency, causing selective death of infected macrophages with impaired infection-induced increase in mitochondrial membrane potential." (PMID 36103894, 2022). "Mechanistically, HPV invasion and infection cause the stimulation of PI3K/AKT/mTOR pathway, increasing protein synthesis and reducing autophagy." (PMID 33920748, 2021). "We found Cbl and Akt1, two genes implicated in the mTOR signaling pathway to be upregulated in every subset from the bone marrow and spleen in response to the secondary infection." (PMID 34975887, 2021). "T-bet directly bound to and activated the expression of various mTOR-activating and metabolic genes, and Th1 cells exhibited high levels of sustained mTOR activity compared with T-bet–deficient effector CD4+ T cells throughout the course of infection." (PMID 32817333, 2020). "The present study illustrates activation of mTOR signaling—mediated by both Raptor-based C1 and Rictor-based C2 mTOR complexes—during infection of cultured human ECs with pathogenic rickettsiae." (PMID 33003310, 2020). "In particular, we found that PABPC1, an RBP whose encoding mRNA harbors a TOP-motif, is induced during infection in an mTOR-dependent fashion." (PMID 32479529, 2020). "As these results suggest a coupled activation of Akt/mTOR and glycolysis, we next investigated the causality between these two processes during infection." (PMID 32385235, 2020). "We demonstrate that the loss of glycolytic metabolism and mTOR activity within the exhausted Ag-expCD4+ T cell population during infection coincides with reduction in T-bet expression." (PMID 32817333, 2020). "In contrast, LMTOR3, the gene encoding a protein responsible for mTOR signal activation, was down-regulated during the early phase of infection, indicating positive regulatory effects of autophagy." (PMID 30789917, 2019). "We also comment on the role of mTOR inhibitors in this case as possible predisposing factor for the infection." (PMID 30911428, 2019). "Among various downstream factors, mTOR is an important mediator through which the PI3K/Akt pathway is linked to infection progress of some viruses." (PMID 31601269, 2019). "In this model, mTOR mutants were hyper-susceptible to M. marinum at higher infection dose; however, when the inoculum size was decreased, the mTOR-deficient zebrafish cleared infection early." (PMID 29441052, 2018). "In a zebrafish model of M. marinum infection, mTOR was shown to be associated with the host resistance to infection." (PMID 29441052, 2018). "The inhibition of PI3-kinase/AKT/mTOR signaling pathway appeared to be increased the risk of infection." (PMID 28932706, 2017). "Infections of primary BMMs with Legionella encoding a functional Dot/Icm system triggers a host-driven suppression of MTOR through ubiquitination-induced degradation of the upstream MTOR regulator Akt that promote inflammation." (PMID 27942021, 2016). "For example, infection with the bacteria, Shigella flexneri, causes amino acid starvation and subsequent downregulation of mTOR to induce autophagy." (PMID 27242787, 2016). "Infection alone or along with 3-MA treatment caused mTOR activation shown by phosphorylation of p70-S6K (Thr389)." (PMID 26757825, 2016). "Differential expression of pathways associated with cellular growth and proliferation such as mTOR signaling and aryl hydrocarbon receptor signaling are also enriched following infection with both strains." (PMID 23516652, 2013). "As a result, the use of mTOR inhibitors was associated with increased risk of infection due to immunosuppression." (PMID 23785409, 2013). "The same was true for the polymorphism in MTOR (rs6701524); when combining the AG with the low prevalent GG genotype, MTOR was significantly associated with infection with M. tuberculosis Beijing strains (p = 0.02)." (PMID 22879892, 2012).
infection (continued). "Furthermore, the decrease in mTOR levels at the late timepoint of infection was determined to be caused by a miRNA (miR-101), which targeted the mRNA of mTOR to reduce its expression." (PMID 40332127, 2025). "Therefore, after infection with A. hydrophila for 24 h, mTOR signaling pathway is activated in loach, which causes inflammation and then drives and regulates the immune response of the body." (PMID 40375996, 2025). "The zebrafish deficient in mTOR are more likely to clear infection early." (PMID 39114448, 2024). "Until recently, the F17 protein was thought to be only involved in morphogenesis; however, Meade and collaborators used the iF17 virus to show that F17 synthesised during late stages of infection in quiescent human fibroblasts binds to the Raptor and Rictor proteins (associated with mTOR)." (PMID 38338659, 2024). "Since the use of immunosuppressant increases the susceptibility to infections, whether the administration of mTOR inhibitors influence infections has been paid attention to in organ transplant." (PMID 38164133, 2023). "Thus, infection induces widespread mitochondrial damage in mTOR-deficient macrophages, causing cytochrome c release and death." (PMID 36103894, 2022). "The finding that in mTOR deficiency, infection with very few ESX-1/ESAT-6-expressing mycobacteria, likely confined to a single phagosome/phagolysosome, causes global loss of mitochondrial membrane potential suggests that there is rapid propagation of the initial localized damage." (PMID 36103894, 2022). "Moreover, mTOR deficiency blunted the small increase in mitochondrial metabolism that was apparent by 24 h post-infection." (PMID 36103894, 2022). "Specifically, exosomal miRNA-99a/b may be associated with infection through the mTOR regulation pathway." (PMID 36061862, 2022). "In addition, infection of endothelial cells with R. conorii in vitro has been associated with the activation of the mechanistic target of rapamycin (mTOR) signaling." (PMID 34698275, 2021). "The discrepancy between the therapeutic effects of the two mTOR inhibitors was further evident in the marked worsening of the infection caused by rapamycin monotherapy compared to an opposing trend toward reduced bacterial load observed with CC214-2 monotherapy in both mouse strains." (PMID 33903099, 2021). "Indeed, many studies have shown varying roles of mTOR in the regulation of autophagy induced by various stressors involving hypoxia, infection, growth factor deficiency, and nutrient deficiency." (PMID 33920772, 2021). "Consistent with decreased levels of phosphorylated mTOR and S6, the infection caused reduction in the phosphorylated levels of 4EBP1 in the livers of the control mice relative to uninfected control mice as well as in infected mutant mice relative to uninfected control and mutant mice." (PMID 32130224, 2020). "Consequently, the number of splenic Ag-experienced (Ag-exp) CD11a+CD49d+ CD4+ T cells, which contain parasite-specific CD4+ T cell populations, was significantly attenuated in mice with a CD4 T cell–specific mTOR deficiency on days 5 and 15 of infection." (PMID 32817333, 2020). "It is confirmed that mTOR activity is also suppressed during infection of macrophages by pathogenic bacteria, which suggests that the process may be beneficial for the host cell." (PMID 30412620, 2018). "In the context of infection, activation of this pathway is associated with an increase in proliferation via induction of β-catenin/Tcf-Lef-dependent transcription, cell survival, and cell migration, as well as enhanced protein synthesis via mTOR activation." (PMID 28401064, 2017). "Although mTOR inhibitors limit virus replication when added at the start of infection, such drugs have little effect on viral protein synthesis, the association of viral mRNAs with polysomes or virus replication when added later in infection." (PMID 27089357, 2016).
infection (continued). "Tumors with hyperactive mTORC1 may be sensitive to treatment with mTOR(C1)-inhibitors such as rapamycin, and indeed, such drugs have been suggested for treating infections and/or tumors caused by EBV, KSHV, HBV, HCV, HPV and HTLV-1." (PMID 24710474, 2012). "For example, SMA patients present with a higher susceptibility to infection and given the immunosuppression which follows prolonged mTOR inhibition, it may be more advantageous to consider compounds capable of activating autophagy independent of mTOR inhibition." (PMID 38259504, 2023). "A concurrent decrease in phosphorylated mammalian target of Rapa (p-mTOR) was observed at different time points post-infection." (PMID 41363843, 2026). "We propose future research directions, including personalized vaccine strategies leveraging microbiota profiling and mTOR modulation, to address the challenges of infection in aging populations and advance precision medicine for healthy aging." (PMID 42169620, 2026). "So, this article aims to outline a mechanistic framework linking infection-driven mTOR activation to post-infectious neuropsychiatric syndromes." (PMID 41462744, 2025). "For example, both mTOR and p-mTOR levels are significantly reduced upon EV-D68 infection, whereas only the p-mTOR level is reduced after EVA71 infection." (PMID 40869312, 2025). "Given these risks, patients receiving PI3K/AKT/mTOR inhibitors require close monitoring for signs of infection, prophylactic antimicrobials when indicated, and timely management of immune-related complications to prevent life-threatening outcomes." (PMID 40072110, 2025). "The expression of mTOR was shown to increase in A549 cells at both the mRNA and protein level up to 24 h post-infection (hpi) with IAV but decrease at 48 hpi." (PMID 40332127, 2025). "More than 80% of toxicities in our cohort were ascribed to CNI alone or in combination with mTOR inhibitor therapy and/or infection." (PMID 40735634, 2025). "Consistent with our cell line findings, components of the mTOR pathway were dephosphorylated 2 hours post infection in primary cultures." (PMID 39791872, 2025). "After infection, both autophagy and mTOR signaling pathway are activated to promote the proliferation and differentiation of immune cells, induce the production of type I IFN and inflammatory factors, and then trigger innate and specific immunity." (PMID 40375996, 2025). "In the context of immune strategies, this has been categorized as defense (anabolic), involving mTOR-mediated immune cell proliferation to combat infection, versus dormancy (catabolic), or tolerance." (PMID 40574888, 2025). "One of the critical side effects of PI3K/AKT/mTOR pathway inhibitors in the treatment of PDEECs is immune suppression, which can lead to life-threatening infections." (PMID 40072110, 2025). "Represses mTOR, in last stages of infection and suppresses viral replication, decreases the expression of the NP." (PMID 39185567, 2025). "We also show that a switch between autophagy suppression and upregulation between the early and later stages was mediated through modulation of the mammalian target of rapamycin (mTOR) activity during infection." (PMID 40042894, 2025). "Previous work has linked activation of S6 kinase and mTOR signaling through EGFR activation during HPV and MmuPV1 infection." (PMID 41165329, 2025). "The nutrient-sensing kinase mTOR is the central negative regulator; stressors such as nutrient deprivation, oxidative stress, or infection inhibit mTOR, thereby activating autophagy, whereas nutrient abundance suppresses autophagic flux." (PMID 41440542, 2025). "We demonstrated that exogenous AbOmpA inhibited autophagy by suppressing AMPK phosphorylation at Thr172 and ULK1 phosphorylation at Ser317, while inducing mTOR under both infection and starvation stress conditions." (PMID 39998213, 2025).
infection (continued). "Inhibition of mTOR by torin reduced infectious virus production and intracellular virus gene expression while improving cell survival during infection." (PMID 40042894, 2025). "Etiological factors were above-target calcineurin inhibitor (CNI) trough levels (48%), combined CNI and mTOR inhibitor therapy (23%), and infection (9%)." (PMID 40735634, 2025). "Viruses frequently exploit host cell stress response mechanisms to reprogram the translational landscape during infection, including core pathways such as the integrated stress response, DNA damage, mTOR signaling, and oxidative stress responses." (PMID 41279401, 2025). "The PI3K, Akt, and mTOR mRNA levels treated with levamisole or baicalin were significantly increased compared to the infection group (p < 0.05)." (PMID 40427533, 2025). "In MERS-CoV infection, inhibition of the mTOR pathway prior to infection resulted in a 60% inhibition of virus replication in epithelial-like cells." (PMID 40426989, 2025). "Dosages of 100 mg/kg baicalin increased p-mTOR protein levels, in contrast with the infection group (p < 0.05)." (PMID 40427533, 2025). "Interferon regulatory factor 8 (IRF8) is an activator of AMPK/mTOR signaling that mediates sterile inflammation and response to infection." (PMID 40507030, 2025). "EVA71 infection recruits mTOR to lysosomes to promote ras homolog enriched in brain (RHEB) interaction and activation via the phosphoinositide 3-kinase (PI3K)/protein kinase B (AKT)/Tuberous sclerosis complex 2 axis." (PMID 40869312, 2025). "Activation of the Akt/mTOR signaling pathway is often involved in the development of innate immune memory following vaccination, infection or exposure to stimuli such as oxLDL." (PMID 41573556, 2025). "Early in infection, mTOR activity is greater as shown by increased levels of p70S6K phosphorylation, whereas, after 20 hpi, levels of phosphorylated p70S6K are dramatically reduced." (PMID 40042894, 2025). "mTOR pathway was found to block TLR2-dependent release of IL-23 in an in vitro model of human monocyte-derived macrophages infection with Mycobacterium tuberculosis." (PMID 40806725, 2025). "Together, these data place mTOR activation downstream of a putative infection-induced miR-126/tsc1a pathway and demonstrate that additional non-mTOR factors mediate the infection phenotype downstream of the miR-126/tsc1a axis." (PMID 38307625, 2024). "This study has importantimplications for the metabolic requirements of innate immune cells duringbacterial infection as well as the clinical use of mTOR inhibitors." (PMID 38767353, 2024). "These experiments demonstrate a clear role for mTOR signaling incontrolling bacterial burden, dissemination, and resolution of infection duringS. aureus SSTI." (PMID 38767353, 2024). "PI3K, Akt and mTOR mRNA expression was downregulated in the infection group compared to that in the control group, while baicalin, levamisole and BMS-1 increased the expression of these components compared to that in the infection group (P < 0.01)." (PMID 39075562, 2024). "This is probably indicative of the pleiotropic contributions that UL38 makes to infection, including activating mTOR, inducing many facets of central carbon metabolism, blocking ER stress, and inhibiting apoptosis (33, –, 35, 49, 50)." (PMID 38117060, 2024). "PP242 (TORKinib) treatment greatly activated MCPyV replication and infection in 293 cells shown by using a transwell infection system, suggesting that mTOR is one of the pathways closely related to the post-transcriptional regulation of LT and LT stability." (PMID 38940554, 2024). "Effects of infection-induced circRNAs on mTOR signaling pathway and its consequences thus warrant further study." (PMID 38263330, 2024). "To test this and define the regulation of the mTOR/autophagy as a mechanistic mediator of the protective effects against infection we observed upon LPD feeding in vivo, we performed studies in vitro using mouse BMDM." (PMID 39349819, 2024).